BANCR (BRAF-activated non-protein coding RNA)
Diseases named in the same sentence as BANCR in open-access papers (continued):
Sharing a sentence is not in itself a finding about the gene and the disease.
lymph node metastasis (12 papers, 2014 to 2024). "High expression of lncRNA BANCR in CRC is associated with lymph node metastasis and the OS of patients with high BANCR expression is shorter." (PMID 33718238, 2021). "Upregulation of lncRNA BANCR may be associated with the lymph node metastasis and poor survival of CRC." (PMID 28969673, 2017). "In this study, we found a high expression level of BANCR in pancreatic cancer tumor tissues and pancreatic cancer cell lines, and the expression of BANCR was positively correlated with lymph node metastasis in pancreatic cancer patients." (PMID 37998732, 2023). "They discovered that the high BANCR expression group was significantly associated with higher histologic grade, advanced TNM stage and more lymph node metastasis." (PMID 29212285, 2017). "Overexpression of BANCR is positively associated with higher histologic grade, advanced TNM stage and lymph node metastasis, affecting the prognosis of cancer patients." (PMID 29212285, 2017). "Interestingly, for the group of patients with the lymph node metastasis, we found the similar result that high lncRNA BANCR expression was related to poor OS (P = 0.004)." (PMID 28969673, 2017). "In the group of patients with lymph node metastasis, we found the similar result that the OS rates were significantly lower in patients with high lncRNA BANCR expression levels than those with low lncRNA BANCR expression levels (P = 0.004)." (PMID 28969673, 2017). "In addition, high expression of lncRNA BANCR was positively correlated with the lymph node metastasis (P < 0.001)." (PMID 28969673, 2017). "What’s more, high BANCR expression was correlated with FIGO (International Federation of Gynecology and Obstetrics) stage, pathological grade, myometrial invasion and lymph node metastasis." (PMID 29212285, 2017). "Univariate analysis identified three prognostic factors: lymph node metastasis; TNM stage; and BANCR expression level." (PMID 24655544, 2014). "First, the pooled results revealed the significant association between high BANCR expression and worse OS and RFS, advanced TNM stage and a high risk of lymph node metastasis, which failed to be concluded by a previous meta-analysis." (PMID 32907530, 2020). "BANCR is highly expressed in CRC and is related with lymph node metastasis and tumor staging." (PMID 28108736, 2017). "Furthermore, the multivariate Cox regression model analysis indicated that high expression of lncRNA BANCR was an independent poor prognostic factor in CRC patients (HR 2.24, 95% CI 1.22–4.16, P = 0.009), regardless of tumor size, depth of invasion, and lymph node metastasis." (PMID 28969673, 2017).
hepatocellular carcinoma (11 papers, 2016 to 2025). A malignant tumor that arises from hepatocytes. "For instance, in bladder cancer and hepatitis B virus–related hepatocellular carcinoma, BANCR levels were notably diminished, making it a promising biomarker and therapeutic target for certain cancers." (PMID 39894218, 2025). "In a study on hepatocellular carcinoma, researchers linked BANCR to MEK: reducing BANCR expression inactivates the MEK pathway." (PMID 41463281, 2025). "BANCR has also been shown to be up-regulated in a hepatocellular cancer cell line compared with normal hepatic cells." (PMID 34409032, 2021). "Over-expression of BANCR in hepatocellular carcinoma cells has been correlated with advanced grade, large tumor dimension, venous intrusion, advanced clinical stage, and poor overall survival." (PMID 34409032, 2021). "BANCR silencing has substantially repressed proliferation and colony construction capability, arrested cells, and induced apoptosis in hepatocellular cancer cells." (PMID 34409032, 2021). "Overexpression of BANCR has been found in many types of cancer such as bladder cancer, esophageal squamous cell carcinoma, and hepatocellular carcinoma." (PMID 28108736, 2017).
retinoblastoma (10 papers, 2016 to 2021). A malignant tumor that originates in the nuclear layer of the retina. "What’s more, overexpression of BANCR was associated with retinoblastoma progression and overall survival of retinoblastoma patients." (PMID 29212285, 2017). "In retinoblastoma, BANCR regulated cell proliferation, migration, and invasion in vitro and overexpressed BANCR expression linked with tumor size, choroidal invasion, and optic nerve invasion." (PMID 26758762, 2016). "In retinoblastoma tissues and cell lines, recent evidence has shown that BANCR is over-expressed and is highly associated with tumor size, choroidal invasion, and optic nerve invasion." (PMID 27043545, 2016). "The authors revealed that suppression of BANCR expression inhibited retinoblastoma cells proliferation and migration." (PMID 29212285, 2017). "Knockdown of BANCR significantly suppresses the proliferation, migration, and invasion of retinoblastoma cells in vitro, thus implying a better prognosis." (PMID 27043545, 2016). "Su at al. revealed that BANCR was overexpressed in retinoblastoma tissues and cell lines." (PMID 29212285, 2017). "lncRNA BANCR also played an important role in retinoblastoma aggressiveness." (PMID 28938549, 2017). "However, only two lncRNAs, BANCR and MEG3, have been associated with retinoblastoma." (PMID 27043545, 2016). "LncRNAs PVT1, AFAP10AS1, HOTAIR, BANCR, H19, DANCR and LINC00202 were up-regulated in retinoblastoma tissues while MT1JP and BDNF-AS were down-regulated." (PMID 32514246, 2020). "Therefore, BANCR may become a new potential target and prognostic factor for retinoblastoma." (PMID 29212285, 2017).
non-small cell lung carcinoma (9 papers, 2014 to 2021). A group of at least three distinct histological types of lung cancer, including non-small cell squamous cell carcinoma, adenocarcinoma, and large cell carcinoma. "Expression of BANCR was analyzed in 113 non-small cell lung cancer (NSCLC) tissues and seven NSCLC cell lines using quantitative polymerase chain reaction (qPCR) assays." (PMID 24655544, 2014). "Furthermore, BANCR expression promoted non-small cell lung cancer cell migration and invasion through regulating E-cadherin, N-cadherin and Vimentin expression, all of which play crucial roles in epithelial-mesenchymal transition (EMT)." (PMID 27514530, 2016). "However, several publications have shown that BANCR could act as a favorable prognostic factor in non-small cell lung cancer and renal carcinoma." (PMID 32907530, 2020). "For instance, it has been reported that lncRNA BANCR enhances the level of apoptosis in NSCLC (non-small cell lung carcinoma) cell lines in vivo by modulating the expression of Bcl-2 and BAX." (PMID 32499679, 2020).
papillary thyroid carcinoma (9 papers, 2014 to 2023). "Another study has revealed association between the presence of BRAF V600E mutation and with lower levels of BANCR in papillary thyroid carcinoma." (PMID 34409032, 2021). "Moreover, high BANCR expression in papillary thyroid cancer has been associated with higher probability of extracapsular invasion and lateral LNM in tumors and a lower probability of bilateral tumors and multifocality in the nearby non-cancerous tissues." (PMID 34409032, 2021). "Here, we investigated BANCR's role in papillary thyroid carcinoma (PTC) by assessing BANCR levels in PTC and matched normal thyroid epithelial tissues from 92 patients using qRT-PCR." (PMID 27462868, 2017). "For example, BANCR (BRAF-activated lncRNA) could increase cell proliferation in papillary thyroid cancer (PTC, PTC accounts for approximately 80% of all THCA in adults), and its levels were significantly higher in PTC." (PMID 29340074, 2017). "However, little is known about the role of BANCR in the development of papillary thyroid carcinoma (PTC)." (PMID 25289082, 2014).
bladder cancer (6 papers, 2016 to 2025). "Conversely, BANCR was downregulated in lung cancer, bladder cancer, and kidney cancer, exhibiting tumor-inhibitory effects." (PMID 39894218, 2025). "In bladder cancer cell lines, over-expression of BANCR has repressed cell proliferation, stimulated apoptotic pathways and suppressed migration." (PMID 34409032, 2021). "To further explore the biological functions of lncRNA BANCR, we detected the cell proliferation, apoptosis and migration by overexpressing BANCR in bladder cancer T24 and SW780 cells." (PMID 27514530, 2016). "The relative expression level of BANCR was measured by using qRT-PCR in bladder cancer tissues and pair-matched adjacent normal bladder tissues from 54 bladder cancer patients." (PMID 27514530, 2016). "Compared with the SV-HUC-1 cell line, the BANCR expression was decreased significantly in bladder cancer cellsT24 and SW780 (**P < 0.01)." (PMID 27514530, 2016). "Furthermore, compared with the SV-HUC-1 cell line, the BANCR expression in bladder cancer cell lines (T24, SW780) was also obviously downregulated." (PMID 27514530, 2016). "The results suggested that BANCR inhibits cell proliferation in bladder cancer cells." (PMID 27514530, 2016). "Moreover, the molecular mechanism by which BANCR was decreased in bladder cancer also should be investigated in the future works." (PMID 27514530, 2016). "Thus, in the present research, we identified the clinical significance of lncRNA BANCR in 54 clinical bladder cancer samples and investigated the effects of BANCR expression on bladder cancer cells in vitro." (PMID 27514530, 2016). "Lastly, we further determined whether BANCR suppressed cell migration in bladder cancer." (PMID 27514530, 2016). "Moreover, further experiments indicated that the overexpression of lncRNA BANCR could inhibit proliferation, induce apoptosis and suppress migration of the bladder cancer cell lines." (PMID 27514530, 2016). "However, the relationship between BANCR and bladder cancer (BC) is largely unclear." (PMID 27514530, 2016). "However, the functions of BANCR in bladder cancer were completely unknown." (PMID 27514530, 2016). "Furthermore, we investigated whether BANCR could induce cell apoptosis in bladder cancer." (PMID 27514530, 2016). "However, the significance of lncRNA BANCR in bladder cancer is completely unknown." (PMID 27514530, 2016). "In contrast, BANCR expression has been displayed to be down-regulated in bladder cancer tissues compared with neighboring non-tumoral sections." (PMID 34409032, 2021).
breast carcinoma (6 papers, 2015 to 2023). "In fact, there is increasing evidence that BANCR is overexpressed in human cancers, such as esophageal squamous cell carcinoma and breast cancer." (PMID 37998732, 2023). "Breast cancer patients with low expression of lncRNA BANCR were significantly different than patients with higher expression of lncRNA BANCR." (PMID 36685962, 2022). "BANCR is significantly correlated to the growth of breast cancer cells." (PMID 33745450, 2021).
osteosarcoma (4 papers, 2017 to 2022). A usually aggressive malignant bone-forming mesenchymal neoplasm, predominantly affecting adolescents and young adults. "For example, SNHG12 participates in regulating IGF1R-induced proliferation and metastasis of osteosarcoma cells by modulating miR-195-5p; BANCR regulates Wnt/β-Catenin signaling pathway by sponging miR-195-5p, thereupon promoting pancreatic cancer progression." (PMID 35037833, 2022). "The altered lncRNA expression profile possessed a total of 9 individuals, yet 7 of them (TUG1, 91H, HULC, BANCR, FGFR3-AS1, HOTTIP, and OMRUL) were overexpressed in osteosarcoma tissues/plasma, and 2 (MEG3 and TUSC7) were down-regulated." (PMID 28415638, 2017). "Among the altered lncRNA profiles, 7 lncRNAs involved TUG1, 91H, HULC, BANCR, FGFR3-AS1, HOTTIP and OMRUL, were notably increased in patients with osteosarcoma and strongly correlated to worse clinical outcomes, indicating that such lncRNAs may play oncogenic roles in maintaining tumor progression." (PMID 28415638, 2017).
pancreatic cancer (4 papers, 2020 to 2023). "BANCR was overexpressed in pancreatic cancer tissues and cells, which was associated with poor clinical outcomes and validated in pancreatic cancer cell lines." (PMID 37998732, 2023). "The expression of BANCR in the established pancreatic cancer stable cell lines PANC-1 is significantly different." (PMID 37998732, 2023). "This inhibitor showed an anticancer effect in the in vitro pancreatic cancer cell model that was mediated by affecting the expression of BANCR." (PMID 37998732, 2023). "This study attempted to explore the therapeutic effect of STM2457 targeting BANCR m6A on pancreatic cancer proliferation, migration, and invasion." (PMID 37998732, 2023). "This study further expands the function of m6A methylation to modify BANCR and provides new ideas for the prevention and treatment of pancreatic cancer invasion and metastasis." (PMID 37998732, 2023). "In this study, we have focused on BANCR as a potential therapeutic target for human pancreatic cancer." (PMID 37998732, 2023). "It is suggested that low expression of BANCR can reduce the proliferation ability of pancreatic cancer cells." (PMID 37998732, 2023). "Remarkably, STM2457 inhibited the proliferation, invasion, and metastasis of pancreatic cancer cells by down-regulating BANCR m6A modifications." (PMID 37998732, 2023). "In this study, the MeRIP-PCR experiment showed that BANCR in pancreatic cancer cells had a high degree of m6A methylation." (PMID 37998732, 2023). "This study demonstrates the promise of BANCR as a new diagnostic and therapeutic target for pancreatic cancer and reveals the therapeutic effect that STM2457 exerts on pancreatic cancer by down-regulating BANCR m6A modifications." (PMID 37998732, 2023). "Based on this, the aim of our study was to investigate the effect of a highly potent and selective first-in-class catalytic inhibitor of METTL3 (STM2457) on BANCR m6A methylation and its malignant biological behaviors in pancreatic cancer." (PMID 37998732, 2023). "In this study, we confirmed the clinical correlation between BANCR and pancreatic cancer and investigated the effect of STM2457 on the modification and expression of BANCR m6A at in vitro levels." (PMID 37998732, 2023). "Further studies showed that pancreatic cancer cell proliferation, migration, and invasion function with BANCR knockdown were weakened." (PMID 37998732, 2023). "The expression of BANCR in pancreatic cancer cell lines SW1990 (11.04 ± 1.26) and PANC-1 (12.77 ± 1.03) was higher than normal pancreatic ductal epithelium cells (HPDECs)." (PMID 37998732, 2023). "This study will further explore the effects of STM2457, a small-molecule inhibitor of METTL3, on the BANCR expression and m6A methylation of pancreatic cancer cells." (PMID 37998732, 2023). "Here, we found that BANCR m6A methylation increased in pancreatic tumor tissues and cells, upregulated BANCR level overexpression, and upregulated BANCR predicted poor prognosis in pancreatic cancer patients." (PMID 37998732, 2023). "The level of BANCR in 77.4% (24/31) of pancreatic cancer tissues (2.45 ± 0.18) was higher than that in the adjacent normal tissues (1.31 ± 0.12)." (PMID 37998732, 2023). "In conclusion, our study demonstrates the potential of BANCR as a promising new diagnostic and therapeutic target for pancreatic cancer and reveals the therapeutic effect of STM2457 on pancreatic cancer mediated by inhibiting BANCR expression." (PMID 37998732, 2023). "The level of BANCR in 31 pancreatic cancer tissues and paired adjacent normal control tissues was detected by RT-qPCR." (PMID 37998732, 2023). "Functional studies in pancreatic cancer cells have not only confirmed the oncogenic effects of BANCR, but also has identified miR-195-5p as a direct target of BANCR through which this lncRNA regulates Wnt/β-catenin pathway." (PMID 34409032, 2021). "In this study, we focused on BANCR as a potential therapeutic target for human pancreatic cancer." (PMID 37998732, 2023).
pancreatic cancer (continued). "The effect of BANCR on the proliferation of pancreatic cancer cells was tested by the CCK8 assay." (PMID 37998732, 2023). "The knockdown BANCR inhibited pancreatic cancer cell proliferation, migration, and invasion." (PMID 37998732, 2023). "This suggests that BANCR is an oncogene that promotes a poor prognosis in pancreatic cancer cells." (PMID 37998732, 2023). "Our experimental data suggest that modification by inhibiting m6A methylation of BANCR may be a promising biomarker and therapeutic target for the treatment of pancreatic cancer patients." (PMID 37998732, 2023). "Therefore, it is suggested that the low expression of BANCR can reduce the proliferation ability of pancreatic cancer cells." (PMID 37998732, 2023). "For example, lncRNA BANCR can inhibit pancreatic cancer progression by modulating miR-195-5p." (PMID 32492657, 2020). "It is suggested that BANCR may play a stimulative role in the development of pancreatic cancer." (PMID 37998732, 2023).
colon cancer (3 papers, 2018 to 2022). "They treated colon cancer cells with pCDNA-BANCR to induce BANCR expression and found that over-expression of BANCR increased translation of p21 which led to cell cycle arrest and induction of apoptosis." (PMID 36076273, 2022). "For example, lncRNA BANCR was expressed differentially in GC and colon cancer." (PMID 32334623, 2020).
endometrial cancer (3 papers, 2018 to 2020). Primary or metastatic malignant neoplasm involving the endometrium (mucous membrane that lines the endometrial cavity). "For example, it has been reported that lncRNA BANCR expression is up-regulated in endometrial cancer and it promotes cancer cell proliferation and tumorgenesis." (PMID 29599647, 2018).
endometriosis (3 papers, 2022 to 2025). The growth of functional endometrial tissue in anatomic sites outside the uterine body. "Another study found that BANCR expression increased gradually during the malignant transformation of endometriosis, and the expression levels of CPNE3 were remarkably upregulated, while those of miR-612 were downregulated (p < 0.05)." (PMID 40364006, 2025).
liver cancer (3 papers, 2020 to 2021). An epithelial or non-epithelial malignant neoplasm that arises from the liver. "Another studies in liver cancer cells has demonstrated the impact of BANCR silencing in impairment of cell proliferation, promotion of cell apoptosis, reduction of invasive properties and down-regulation of vimentin, and up-regulation of E-cadherin expression." (PMID 34409032, 2021). "For example, BANCR can be used as a potential therapeutic target for liver neoplasms, NEAT1 is necessary for liver neoplasm marker CD44 expression, and LINC00473 promotes the progression of liver cancer by acting as microRNA-195 ceRNA and increasing HMGA2 expression." (PMID 35058974, 2021).
atherosclerosis (2 papers, 2017 to 2024). A disease characterized by the build-up of fatty material and calcium deposition in the arterial wall resulting in partial or complete occlusion of the arterial lumen. "Jiang and colleagues found an interaction between lncRNA BANCR and miR-34c; in the plasma of patients with atherosclerosis, the expressions of BANCR and miR-34c were increased and decreased, respectively." (PMID 39194749, 2024). "In our study, we firstly measured the BANCR expression in the atherosclerosis tissues." (PMID 29383102, 2017). "We first measured the BANCR expression in the atherosclerosis tissues." (PMID 29383102, 2017).
clear cell renal cell carcinoma (2 papers, 2018 to 2020). "Nevertheless, the role of BANCR in clear cell renal cell carcinoma (ccRCC) is still not fully understood." (PMID 30200918, 2018).
diabetic retinopathy (2 papers, 2022 to 2023). "BANCR is overexpressed in diabetic retinopathy patients and has been shown to cause apoptosis of retinal pigment epithelial cells." (PMID 35599572, 2022). "There is no research proving the expression of Lnc-RNA BANCR in aqueous or vitreous humor either in humans or animals, and the specific molecular mechanisms of BANCR in diabetic retinopathy remain unknown." (PMID 37762249, 2023).